TCF19 (transcription factor 19)
Description:
Potential transcription factor that may play a role in the regulation of genes involved in cell cycle G1/S transition. May bind to regulatory elements of genes, including the promoter of the transcription factor FOXO1.
Synonyms: TCF-19; SC1
Tractability: No criterion of Open Targets' tractability assessment is met for any kind of drug.
Safety:
Unwanted effects reported when the protein is acted on. In parentheses: how it was acted on, where the effect was seen, and who reports it.
rash (source: ClinPGx)
severe cutaneous adverse reactions (source: ClinPGx)
Gene: Protein-coding gene on chromosome 6 (31,158,331 to 31,167,159, forward strand). Ensembl gene ENSG00000137310.
Subcellular location: Nucleus
Subcellular location (Human Protein Atlas): Nucleoli; Nucleoplasm
Pathways (Reactome):
Chromatin organization: Interaction of NuRD complexes with transcription factors
Gene Ontology:
Molecular function: protein binding
Biological process: regulation of gene expression
Cellular component: nucleoplasm; nucleus
Genetic constraint (gnomAD): Loss-of-function variants: 11 observed, 20.48 expected, observed/expected ratio (o/e) 0.54, 90% interval 0.34 to 0.89. The upper end of that interval is the gene's LOEUF score, 0.89, which puts it in group 3 of 6, group 1 being the genes least tolerant of losing a copy. Missense variants: 360 observed, 430.64 expected, observed/expected ratio (o/e) 0.84, 90% interval 0.77 to 0.91. Synonymous variants: 169 observed, 173.23 expected, observed/expected ratio (o/e) 0.98, 90% interval 0.86 to 1.11.
Homologues: Orthologues: chimpanzee TCF19 (99% identical), macaque TCF19 (96% identical), pig TCF19 (87% identical), rabbit TCF19 (87% identical), dog TCF19 (72% identical), guinea pig TCF19 (66% identical), rat Tcf19 (62% identical), mouse Tcf19 (61% identical), zebrafish tcf19l (42% identical), tropical clawed frog tcf19 (40% identical), Caenorhabditis elegans gldi-3 (25% identical).
Diseases named in the same sentence as TCF19 in open-access papers:
TCF19 is named in the same sentence as 62 diseases in open-access papers, as found by Europe PMC text mining. Sharing a sentence is not in itself a finding about the gene and the disease. The quoted sentences say what the papers report.
type 1 diabetes (8 papers, 2013 to 2025). "Transcription factor TCF19 is known as a regulator of pancreatic β cell mass and as a risk locus for type 1 diabetes." (PMID 40962957, 2025). "The TCF19 gene encodes a transcription factor involved in regulating cell proliferation and differentiation and has been implicated in type 1 diabetes where it appears to act as a regulator of β-cell mass in the pancreas." (PMID 34440439, 2021). "Transcription factor 19 (TCF19) is a gene associated with type 1 diabetes (T1DM) and type 2 diabetes (T2DM) in genome-wide association studies." (PMID 34436454, 2021). "TCF19 was suggested as a late growth-regulated gene related to the risk of type 1 diabetes and psoriasis vulgaris, playing an important role in the transcription of genes required for the later stages of cell cycle progression." (PMID 24987808, 2014). "Recently, a novel type 1 diabetes association locus was identified at human chromosome 6p31.3, and transcription factor 19 (TCF19) is a likely causal gene." (PMID 23860123, 2013). "Among other genes identified in the CIT analysis were TCF19, which has been associated with type 1 diabetes through GWAS, and CAMK1D, which has been associated with type 2 diabetes This supports the role of DNA methylation as a direct mediator between genetic variation and metabolic phenotypes." (PMID 27322064, 2016). "TCF19 is located on chromosome 6p21.3 close to MHC region in human and its potential role in the etiology of Type 1diabetes (an autoimmune disease) has been suggested." (PMID 24523889, 2014).
lung cancer (6 papers, 2022 to 2025). A malignant neoplasm involving the lung. "The contribution of TCF19 to tumor progression by controlling cellular proliferation has been reported in gastric cancer, hepatocellular carcinoma, non‐small cell lung cancer, colorectal cancer, and liver cancer." (PMID 40952912, 2025). "TCF19 promoted the proliferation of various cancer cells, such as lung cancer and head and neck cancer." (PMID 36233194, 2022). "It has been reported recently that TCF19 influences the effect of immunotherapy in lung cancer through nanotechnology by regulating the polarity of the tumor-associated macrophages." (PMID 36111242, 2022). "Recently, TCF19 has been proposed as a driver of cell proliferation in lung cancer." (PMID 40962957, 2025).
gastric cancer (5 papers, 2013 to 2025). A primary or metastatic malignant neoplasm involving the stomach. "Ji, Xu, and Miao further reported that TCF19 was highly expressed in cancer cells associated with head and neck SCC, liver cancer, and gastric cancer." (PMID 36111242, 2022). "Studies in gastric cancer and insulinoma cells have shown that TCF19 regulates the expression of G1 (e.g., cyclins A and E) and G2/M (cyclin B) cyclins, and BIM, but its role in melanoma is not known." (PMID 29650805, 2018). "In addition, ectopic expression of TCF19 enhanced gastric cancer cell growth." (PMID 24069310, 2013).
hepatocellular carcinoma (5 papers, 2019 to 2025). A malignant tumor that arises from hepatocytes. "Genes, such as CDCA3, KIF15, and TCF19, are linked with the proliferation of various cancer cells, such as oral cancer, pancreatic cancer, and hepatocellular carcinoma cells, but these genes may be responsible for the proliferation of BRCA cells." (PMID 31311202, 2019). "In addition, TCF19 levels have been associated with the risk of head and neck cancer and it has proven prognostic potential for colorectal cancer, renal clear cell carcinoma, endometrial cancer and hepatocellular carcinoma patients." (PMID 40952912, 2025). "A growing body of evidence suggests that TCF19 plays an important role in many types of cancer, including colorectal cancer, non-small cell lung cancer, renal clear cell carcinoma, hepatocellular carcinoma, and head and neck cancer." (PMID 38579171, 2024). "A recent study showed that the PHD finger of TCF19 is necessary for regulating hepatocellular carcinoma cell proliferation through its H3K4me3 binding ability." (PMID 38579171, 2024). "Similar to CCHCR1, TCF19 has been associated with diseases, including diabetes, HBV-related chronic hepatitis B, cirrhosis, hepatocellular carcinoma, non-small cell lung cancer, squamous cell carcinoma of the head and neck (SCCHN) and colorectal cancer." (PMID 38128007, 2023).
autoimmune disease (4 papers, 2014 to 2026). A disorder resulting from loss of function or tissue destruction of an organ or multiple organs, arising from humoral or cellular immune responses of the individual to their own tissue constituents. "TCF19 and a potential deleterious missense variation (rs2073724) were identified to be associated with multiple autoimmune diseases and human cancers." (PMID 38579171, 2024).
colorectal cancer (4 papers, 2022 to 2025). A primary or metastatic malignant neoplasm that affects the colon or rectum. "Du WB reported that TCF19 was significantly upregulated in colorectal cancer and TCF19 was closely related to the progression of malignancy, distant metastasis, and poor prognosis of colorectal cancer." (PMID 36111242, 2022).
diabetes (4 papers, 2013 to 2023). "Although one of many genes associated with diabetes in GWAS, TCF19 is unusual in having associations with both types of diabetes." (PMID 34436454, 2021). "With respect to diabetes susceptibility, individuals with genetic variants of TCF19 may be unable to properly regulate β-cell responses to DNA damage and inflammatory insults, therefore predisposing them to increased β-cell apoptosis." (PMID 34436454, 2021). "The exact mechanism of how TCF19 modulates these inflammatory and DDR genes to promote diabetes susceptibility requires further investigation." (PMID 34436454, 2021). "We initially identified transcription factor 19 (Tcf19) in a microarray of islet gene expression in mouse models of obesity and diabetes." (PMID 23860123, 2013). "This brings to light an interesting crosstalk between the inflammatory and DNA damage pathways in the β-cell and suggests how alterations in TCF19 expression or function may contribute to diabetes pathogenesis in both T1DM and T2DM." (PMID 34436454, 2021). "However, little is known about its role in diabetes pathogenesis or the effects of TCF19 gain-of-function." (PMID 34436454, 2021). "We examined the effects of Tcf19 knockdown on several transcriptionally regulated genes involved in the UPR primarily selected as genes that were known to change in response to ER stress signals and/or diabetes in the islet." (PMID 23860123, 2013).
non-small cell lung carcinoma (4 papers, 2022 to 2024). A group of at least three distinct histological types of lung cancer, including non-small cell squamous cell carcinoma, adenocarcinoma, and large cell carcinoma. "TCF19 gene can promote the proliferation of non-small cell lung cancer cells by inhibiting FOXO1." (PMID 36712848, 2022).
breast carcinoma (3 papers, 2017 to 2025). "Currently, a study showed that TCF19 might be linked with the proliferation of breast cancer cells." (PMID 36233194, 2022). "TCF19 depletion compromises the proliferation and foci formation capacity of colorectal, head and neck squamous carcinoma and breast cancer cell lines." (PMID 40952912, 2025). "In conclusion, the current study showed that CCNE2, CDCA5, RAD51, TCF19, KNTC1, MCM10, and NEIL3 might contribute to EPT-related tumorigenesis in breast cancer, with CCNE2 might be a sensitive risk indicator of breast cancer risk in women using MHT." (PMID 36233194, 2022).
COVID-19 (3 papers, 2023 to 2025). A disease caused by infection with severe acute respiratory syndrome coronavirus 2. "By conducting SMR and HEIDI methods, several non-MHC region SNPs were identified as common shared genetic loci including rs143334143 (TCF19), rs2277732 (DPP9), rs77534576 (DLX3), and rs13081151 (FLT1P1), among others, which were significantly associated with OA-critical COVID-19 combined trait." (PMID 37398645, 2023). "Among them, HLA-C, TCF19, and ADAM15 were shared by PrCa and the two COVID-19 severity phenotypes, while CCHCR1 was shared by PrCa and all three COVID-19 phenotypes." (PMID 41210689, 2025).
insulinoma (3 papers, 2013 to 2021). "We have previously demonstrated that siRNA-mediated knockdown of Tcf19 in rat insulinoma INS-1 cells reduces β-cell proliferation and survival and impairs cell cycle progression beyond the G1/S checkpoint." (PMID 34436454, 2021). "Little is known about Tcf19, and we now show that it plays a role in both proliferation and apoptosis in insulinoma cells." (PMID 23860123, 2013). "siRNA-mediated knockdown of Tcf19 in the INS-1 insulinoma cell line, a β-cell model, results in a decrease in proliferation and an increase in apoptosis." (PMID 23860123, 2013). "TCF19 is expressed in human insulinoma at levels similar to normal islets from obese donors, suggesting that it is not highly upregulated in β-cell tumors." (PMID 23860123, 2013). "To examine the direct role of Tcf19 in cell cycle progression, we used siRNA-mediated knockdown of Tcf19 in INS-1 cells, a rat insulinoma cell line." (PMID 23860123, 2013). "We next wanted to determine if increased levels of TCF19 could drive β-cell proliferation, and therefore, we overexpressed hsTCF19 in INS-1 rat insulinoma cells." (PMID 34436454, 2021). "The expression of TCF19 in human insulinoma tissue was not significantly above that in normal islet tissue from obese donors, suggesting that Tcf19 is not dramatically upregulated in this form of cancer." (PMID 23860123, 2013).
melanoma (3 papers, 2018 to 2026). A malignant, usually aggressive tumor composed of atypical, neoplastic melanocytes. "Depletion of TCF19 led to melanoma cell death, and TCF19 expression levels were associated with poor patient survival." (PMID 29650805, 2018). "Indeed, analysis of the TCGA cutaneous melanoma dataset revealed that BRD4 and TCF19 were positively associated in melanoma and that the levels of TCF19 inversely correlated with patient's survival (P = 8.3 × 10−3)." (PMID 29650805, 2018). "We noted that TCF19 is expressed in NRAS‐mutant melanoma cells and in melanocytes, albeit at lower levels." (PMID 29650805, 2018). "Depletion of TCF19 with two different shRNA constructs led to an increase of cells in G2/M followed by apoptosis of NRAS‐mutant melanoma cells." (PMID 29650805, 2018). "We further discovered that co‐targeting BET and MEK downregulates TCF19 and that this transcription factor is required for melanoma cell survival." (PMID 29650805, 2018). "In any case, the function of TCF19 in NRAS‐mutant melanoma, especially in BRAF/MAPK inhibitor and immune therapy resistance, is worthy to study further to better understand the mechanisms of how TCF19 is upregulated in NRAS‐mutant melanoma and how it governs the resistance to immune therapy." (PMID 29661909, 2018). "Taken together, these results indicate that the combination of BETi/MEKi perturbs the cell cycle machinery and activates apoptotic signaling in NRAS‐mutant melanoma cells in part by synergistically downregulating the PHD‐type zinc finger domain containing transcription factor TCF19." (PMID 29650805, 2018). "The requirement of TCF19 for melanoma cell survival, suggests that this transcription factor could play an important role in this disease." (PMID 29650805, 2018). "TCF19 might participate in managing immunosuppression in NRAS‐mutant melanoma cells." (PMID 29661909, 2018). "Our results raise the possibility that the synergistic repression of the transcription factor TCF19 triggered by concomitant BET and MEK inhibition renders NRAS‐mutant melanoma cells more vulnerable to apoptosis." (PMID 29650805, 2018). "The combination therapy of BRD4 inhibitor (JQ1) plus MEK inhibitor (PD901) synergistically downregulated the transcription factor 19 (TCF19), increased apoptosis in vivo, reduced the growth of NRAS‐mutant melanoma, and prolonged the survival of mice which resisted to MAPK inhibitors and ICIs." (PMID 41492362, 2026). "Additionally, TCF19 levels positively correlated with BRD4 protein levels and sensitivity to BETi in NRAS‐mutant melanoma cells (r = −0.740, P = 0.023)." (PMID 29650805, 2018). "We next explored the biological effects of blocking TCF19 in NRAS‐mutant cells, as the role of this PHD‐type zinc finger‐containing domain transcription factor has not been previously investigated in melanoma." (PMID 29650805, 2018).
Crohn disease (2 papers, 2020 to 2022). A gastrointestinal disorder characterized by chronic inflammation involving all layers of the intestinal wall, noncaseating granulomas affecting the intestinal wall and regional lymph nodes, and transmural fibrosis. "Our analysis resulted in five candidate genes corresponding to two of the major IBD subtypes: UBE2L3 and SLC22A4 for Crohn’s Disease and TCF19, C6orf47 and SNAPC4 for Ulcerative Colitis." (PMID 34968289, 2020).
psoriasis (2 papers, 2023 to 2025). An autoimmune condition characterized by red, well-delineated plaques with silvery scales that are usually on the extensor surfaces and scalp. "This hypothesis offers aplausible explanation for the findings obtained in studies that have focused onPou5f1 polymorphisms associated with psoriasis, especially taking into account theassociation between Tcf19 and this disease." (PMID 40771854, 2025).
type 2 diabetes (2 papers, 2015 to 2016). "We confirmed associations with type 2 diabetes for five of the seven SNPs (TMEM154-rs6813195, FAF1-rs17106184, POU5F1/TCF19-rs3130501, ARL15-rs702634 and ABCB9/MPHOSPH9-rs4275659)." (PMID 25799151, 2015). "A trans-ethnic meta-analysis of type 2 diabetes genome-wide association studies has identified seven novel susceptibility variants in or near TMEM154, SSR1/RREB1, FAF1, POU5F1/TCF19, LPP, ARL15 and ABCB9/MPHOSPH9." (PMID 25799151, 2015).
aortic stenosis (1 paper, 2025). Aortic valve stenosis is a aortic valve disease caused by the incomplete opening of the aortic valve. "In heart tissue biopsies from patients with aortic stenosis, TCF19 and ATAD2 abundance were positively correlated with endothelial cell proliferation." (PMID 40962957, 2025). "To validate these findings in human heart tissue, we assessed the abundance of ATAD2 and TCF19 in left ventricular biopsies from patients with aortic stenosis (n = 7)." (PMID 40962957, 2025).
atherosclerosis (1 paper, 2025). A disease characterized by the build-up of fatty material and calcium deposition in the arterial wall resulting in partial or complete occlusion of the arterial lumen. "Interestingly, Tcf19 may also beinvolved in inflammatory responses, thus linking our findings to the dataobtained using atherosclerosis models." (PMID 40771854, 2025).
cardiac hypertrophy (1 paper, 2025). "In conclusion, we found an association of TCF19 and ATAD2 expression with endothelial cell proliferation during cardiac hypertrophy in mice and humans." (PMID 40962957, 2025). "Downregulation of TCF19 and ATAD2 is associated with endothelial cell cycle arrest and an impaired angiogenic response to VEGF signaling that may promote the transition from compensated cardiac hypertrophy to heart failure." (PMID 40962957, 2025).
heart failure (1 paper, 2025). Inability of the heart to pump blood at an adequate rate to meet tissue metabolic requirements. "In contrast, no significant regulation could be found after experimental myocardial infarction, indicating that the regulation of Tcf19 and Atad2 may be specific for heart failure with more pronounced cardiac myocyte hypertrophy." (PMID 40962957, 2025). "Thus, we conclude that TCF19 and ATAD2 control a gene expression network involved in endothelial cell proliferation and angiogenesis and their downregulation is linked to the cell cycle arrest observed at the transition to heart failure." (PMID 40962957, 2025). "Further studies are needed to identify signaling cascades that lead to the downregulation of TCF19 and ATAD2 in heart failure." (PMID 40962957, 2025). "From a translational point of view, therapeutic restoration of TCF19 and ATAD2 expression could improve the angiogenic capacity of endothelial cells in the heart and provide benefit for patients with heart failure." (PMID 40962957, 2025).
hypotrichosis (1 paper, 2020). A congenital condition, usually due to genetic aberrations, that is characterized by a lack of hair growth on the head and/or body. "Although the deletion encompasses several other genes (C6orf15, PSORS1C1, PSORS1C2, CCHCR1 and part of TCF19), these patients show a phenotype resembling that of PSD without hypotrichosis." (PMID 31663161, 2020).
kidney carcinoma (1 paper, 2022). Primary or metastatic malignant neoplasm involving the kidney. "The results indicated that TCF19 can be used as a potential indicator of the extent of the response generated toward renal cancer immunotherapy." (PMID 36111242, 2022).
lung adenocarcinoma (1 paper, 2022). A carcinoma that arises from the lung and is characterized by the presence of malignant glandular epithelial cells. "Daniela Ruggiero reported the increased level of expression of the TCF19 gene in two major histological subtypes (squamous cell carcinoma (SCC) and lung adenocarcinoma) and revealed that TCF19 promoted the progression of the cell cycle in NSCLC cells." (PMID 36111242, 2022).
lymph node metastasis (1 paper, 2024). "Similarly, patients with lymph node metastasis exhibited higher TCF19 levels than those without." (PMID 38579171, 2024).